ASPG (asparaginase)
Description:
Exhibits lysophospholipase, transacylase, PAF acetylhydrolase and asparaginase activities (By similarity). Can catalyze three types of transacylation reactions: (1) acyl transfer from 1-acyl-sn-glycero-3-phosphocholine (1-acyl-GPC) to the sn-1(3) positions of glycerol and 2-acylglycerol (sn-1 to -1(3) transfer), (2) acyl transfer from 1-acyl-GPC to the sn-2 positions of 1-acyl-GPC, 1-acyl-sn-glycero-3-phosphoethanolamine (1-acyl-GPE), and other lysophospholipids (sn-1 to -2 transfer) and (3) acyl transfer from 2-acyl-GPC to the sn-1 position of 2-acyl-GPC and 2-acyl-GPE (sn-2 to -1 transfer) (By similarity). Mediates the synthesis of 1-arachidonoyl species of phospholipids by transferring the arachidonoyl residue from 2-arachidonoyl lysophospholipid to the sn-1 position of 2-acyl lysophospholipid (By similarity).
Synonyms: LysoLP; C14orf76; hASNase1; GPA/WT
Tractability: No criterion of Open Targets' tractability assessment is met for any kind of drug.
Gene: Protein-coding gene on chromosome 14 (104,085,537 to 104,115,582, forward strand). Ensembl gene ENSG00000166183.
Pathways (Reactome):
Metabolism: Aspartate and asparagine metabolism
Gene Ontology:
Molecular function: protein binding; 1-alkyl-2-acetylglycerophosphocholine esterase activity; acyltransferase activity, transferring groups other than amino-acyl groups; asparaginase activity; phosphatidylcholine lysophospholipase activity; phosphatidylethanolamine lysophospholipase activity
Biological process: L-amino acid metabolic process; amino acid metabolic process
Cellular component: cytosol
Genetic constraint (gnomAD): Loss-of-function variants: 52 observed, 53.45 expected, observed/expected ratio (o/e) 0.97, 90% interval 0.78 to 1.23. The upper end of that interval is the gene's LOEUF score, 1.23, which puts it in group 5 of 6, group 1 being the genes least tolerant of losing a copy. Missense variants: 731 observed, 687.01 expected, observed/expected ratio (o/e) 1.06, 90% interval 1 to 1.13. Synonymous variants: 365 observed, 309.14 expected, observed/expected ratio (o/e) 1.18, 90% interval 1.08 to 1.29.
Homologues: Orthologues: chimpanzee ASPG (98% identical), macaque ASPG (94% identical), pig ASPG (81% identical), mouse Aspg (79% identical), rat Aspg (78% identical), guinea pig ASPG (69% identical), rabbit ASPG (66% identical), dog ASPG (58% identical), tropical clawed frog aspg (52% identical), zebrafish aspg (50% identical), Drosophila melanogaster CG6428 (42% identical), Caenorhabditis elegans C27A7.5 (41% identical), and 1 more.
Diseases named in the same sentence as ASPG in open-access papers:
ASPG is named in the same sentence as 149 diseases in open-access papers, as found by Europe PMC text mining. Sharing a sentence is not in itself a finding about the gene and the disease. The quoted sentences say what the papers report.
acute lymphoblastic leukemia (192 papers, 2013 to 2026). Leukemia with an acute onset, characterized by the presence of lymphoblasts in the bone marrow and the peripheral blood. "Asparaginase-associated pancreatitis complicates 2-10% of patients treated for acute lymphoblastic leukemia, causing morbidity and discontinuation of asparaginase administration." (PMID 38817959, 2023). "Asparagine synthetase (ASNS) is associated with asparaginase therapy in acute lymphoblastic leukemia." (PMID 35625787, 2022). "Trypsin-encoding PRSS1-PRSS2 variations influence the risk of asparaginase-associated pancreatitis in children with acute lymphoblastic leukemia." (PMID 34249950, 2021). "It has also been associated with asparaginase-related thrombosis and pancreatitis in the treatment of acute lymphoid leukemia in Caucasians, diabetes mellitus, autoimmune diseases, endometriosis, and knee osteoarthritis." (PMID 32934782, 2020). "For example, anti-PEG Ab were closely associated with the rapid clearance of PEG-asparaginase in a subgroup of patients treated for acute lymphoblastic leukemia." (PMID 24588936, 2014). "Moreover, ATF5 gene polymorphisms that appear to enhance activity at the ASNS promoter are linked to asparaginase treatment resistance in childhood acute lymphoblastic leukemia." (PMID 34065488, 2021). "Pegylated asparaginase (pegaspargase), a form of Escherichia coli L-asparaginase that is covalently linked to polyethylene glycol, has proven effective against acute lymphoblastic leukemia and ENKTL with less toxicity and a longer half-life than free L-asparaginase." (PMID 27093153, 2016). "Asparaginase is an essential component of acute lymphoblastic leukemia (ALL) therapy, yet its associated toxicities often lead to treatment discontinuation, increasing the risk of relapse." (PMID 38287133, 2024). "Asparaginase is a critical component of therapy for childhood acute lymphoblastic leukemia (ALL), but it is commonly associated with allergy, which results in morbidity and poorer outcomes." (PMID 36980715, 2023). "Asparaginase is an essential treatment for acute lymphoblastic leukemia – the most common malignant disease in children – with AP as a common adverse event occurring in about 5–10% of cases, which is the most frequent cause of discontinuing the asparaginase treatment." (PMID 36609875, 2023). "Asparaginase is an integral component of pediatric acute lymphoblastic leukemia (ALL) chemotherapy regimens and is known to be associated with improved long-term outcomes and survival." (PMID 33014332, 2020). "Allergy, pancreatitis and thrombosis are common side-effects of childhood acute lymphoblastic leukemia (ALL) treatment that are associated with the use of asparaginase (ASNase), a key component in most ALL treatment protocols." (PMID 28574850, 2017). "Other evidence suggests that the administration of the enzyme asparaginase in the treatment of pediatric acute lymphoblastic leukemia improved the cure rate." (PMID 40944200, 2025). "Asparaginase is an enzyme and key component in the treatment of acute lymphoblastic leukemia (ALL), the most common childhood cancer." (PMID 39798881, 2025). "The average Chinese resident needed to work 5.3 days to afford a 4-week course of induction therapy with asparaginase for a standard child with acute lymphoblastic leukaemia, for which the copayment was ¥512.2 (US$ 79.4)." (PMID 39780997, 2025). "Acute lymphoblastic leukemia (ALL) cells are unable to synthesize asparagine de novo, and therefore are susceptible to asparagine depletion by PEGylated E. coli asparaginase (PEG-ASNase)." (PMID 40177540, 2025). "Acute lymphoblastic leukemia (ALL) is the most common childhood cancer, and survival rates have significantly improved with risk-adapted chemotherapy protocols that include asparaginase as a key component." (PMID 40895695, 2025).
acute lymphoblastic leukemia (continued). "The enzyme asparaginase (ASPase) is an essential drug in the treatment protocols for acute lymphoblastic leukemia (ALL), particularly in children and young adults." (PMID 40733123, 2025). "The affordability of chemotherapy medicines for acute lymphoblastic leukaemia was least in north-west and south-west China, where 7.4 days’ and 6.7 days’ income, respectively, was required to afford a course of asparaginase induction therapy." (PMID 39780997, 2025). "Asparaginase, an enzyme that breaks down asparagine, has been used in treating acute lymphoblastic leukaemia (ALL) but is now being explored in solid tumours." (PMID 39796683, 2024). "Asparagine and glutamine depletion operated by the drug Asparaginase (ASNase) has revolutionized therapy in pediatric patients affected by Acute Lymphoblastic Leukemia (ALL), bringing remissions to a remarkable 90 % of cases." (PMID 39170541, 2024). "Asparaginase has been used to treat acute lymphoblastic leukaemia in the clinic for decades by reducing levels of circulating ASN." (PMID 39332495, 2024). "Asparaginase is a critical component of chemotherapy for pediatric acute lymphoblastic leukemia (ALL), but its use is often complicated by asparaginase-associated pancreatitis (AAP)." (PMID 39564382, 2024). "The use of asparaginase is well-established as part of multi-agent chemotherapeutic regimens in pediatric and adult acute lymphoblastic leukemia (ALL)." (PMID 38951899, 2024). "Asparaginase plays an important role in the chemotherapeutic regimens to treat acute lymphoblastic leukemia (ALL)." (PMID 38888368, 2024). "Asparaginase (ASNase) is an FDA-approved drug to treat acute lymphoblastic leukemia (LLA); however, it exhibits high immunogenicity which often leads to discontinuation of treatment." (PMID 37765229, 2023). "For example, the depletion of blood asparagine by using asparaginase is involved in modern clinical treatments of childhood acute lymphoblastic leukemia (ALL) because ALL cells are in great need of exogenous asparagine." (PMID 38023181, 2023). "Asparaginase treatments, such as pegaspargase, reduce asparagine levels and were approved for acute lymphoblastic leukemia." (PMID 37333177, 2023). "Pegaspargase, a covalent conjugate of polyethylene glycol (PEG), and Asparaginase are both used to treat acute lymphoblastic leukemia (ALL)." (PMID 38044938, 2023). "With respect to upstream factors, asparaginase, a drug for acute lymphoblastic leukemia, was detected in the upstream analysis and is able to arrest the cell cycle." (PMID 36609486, 2023). "Since the discovery of asparaginase as an anti-cancer agent for treating acute lymphoblastic leukemia, ASNS and Asn deprivation have been important areas of research." (PMID 37111157, 2023). "Since the 1960s, asparaginase (ASP) has been used to treat children with acute lymphoblastic leukemia (ALL)." (PMID 38067249, 2023). "One example is asparaginase that depletes both asparagine and glutamine in serum, which has been widely used to treat childhood acute lymphoblastic leukemia." (PMID 36793607, 2023). "Pegylated (PEG)-asparaginase is an established treatment for acute lymphoblastic leukemias that exhibits an antitumor effect by depleting asparagine, an amino acid essential for leukemia cell protein synthesis." (PMID 36741726, 2023). "This approach has succeeded on the basis of the asparaginase template whereby asparagine deprivation for acute lymphoblastic leukaemia is deployed in the context of multimodality therapy rather than as monotherapy." (PMID 36903394, 2023). "One study on acute lymphoblastic leukaemia reported an association between the SOD2 gene variant rs4880 and hepatotoxicity in patients undergoing asparaginase-based therapy." (PMID 37469404, 2023). "Adverse reactions during and shortly after infusing asparaginase for the treatment of acute lymphoblastic leukemia can increase in severity with later doses, limiting further use and increasing relapse risk." (PMID 35997335, 2022).
acute lymphoblastic leukemia (continued). "In fact, L-asparagine depletion via asparaginase is an approved therapeutic strategy for acute lymphoblastic leukemia, and it is being investigated in solid tumors." (PMID 35286311, 2022). "In fact, L-asparagine depletion via asparaginase administration is an approved therapy for acute lymphoblastic leukemia." (PMID 35286311, 2022). "We chose intramuscular injection for our experiments because it is a common delivery mode for asparaginase in the treatment of acute lymphoblastic leukemia (ALL)." (PMID 36678770, 2022). "This mimics the transient hyperammonemia in pediatric oncology patients treated with asparaginase for acute lymphoblastic leukemia and non-Hodgkin lymphoma patients." (PMID 35997335, 2022). "Clinical data published over the last two decades suggests that asparaginase is a vital element in the treatment of acute lymphoblastic leukaemia (ALL)." (PMID 35055502, 2022). "Erythrocyte-encapsulated asparaginase (eryaspase) has less toxicity and improves patient survival in clinical trials for the treatment of patients with pancreatic cancer or acute lymphocytic leukemia when combined with chemotherapy." (PMID 35178349, 2022). "Attempts to test the effectiveness of Acinetobacter glutaminasificans glutaminase-asparaginase against acute lymphoblast leukemia in patients were discontinued due to strong side effects, presumably due to high glutaminase activity." (PMID 35335974, 2022). "Asparaginase is a mainstay of chemotherapy for acute lymphoblastic leukemia (ALL) but is one of the top five therapeutic compounds known to cause adverse drug reactions." (PMID 35997335, 2022). "While bacterial-derived asparaginase has been approved to treat acute lymphoblastic leukemia and non-Hodgkin lymphoma, the therapeutic efficacies of other amino acids- depleting enzymes in multiple types of cancers are still under clinical investigation." (PMID 35178349, 2022). "Asparaginase, which reduces plasma asparagine, has also been used to treat childhood acute lymphoblastic leukaemia, and arginine deiminase has been shown to have antitumour activity." (PMID 35367410, 2022). "Purified asparaginase from E. coli and Erwinia chrysanthemi was used clinically to treat the acute lymphoblastic leukemia, but it showed allergic side effects which led to death." (PMID 35055502, 2022). "During the last 50 years, bacterial asparaginase have been widely used for acute lymphoblastic leukemia treatment." (PMID 36405587, 2022). "Asparaginase erwinia chrysanthemi (recombinant)-rywn) has been approved as part of the treatment for acute lymphoblastic leukemia for patients who have developed hypersensitivity to E. coli-derived asparaginase, which was approved in 1978." (PMID 35164339, 2022). "At present, asparaginase has been developed for the treatment of childhood acute lymphoblastic leukemia (ALL)." (PMID 36553562, 2022). "The context of that study was to investigate the genetic basis for allergic reactions which occur in up to 45% of patients receiving asparaginase derived from Escherichia coli or Erwinia chrysanthemi for treatment of childhood acute lymphoblastic leukemia." (PMID 35591856, 2022). "In addition, the A6E mutation codon could be incorporated into the ASNS gene of patients with acute lymphoblastic leukemia to minimize the risk of developing a resistance to the asparaginase treatment, as A6E mutation can block the attempt at ASNS overexpression by the cancer cells." (PMID 33916846, 2021). "Targeting asparagine using asparaginase has been approved for treating acute lymphoblastic leukemia." (PMID 33477430, 2021). "The present work focuses on the enzyme asparaginase, used for the treatment of acute lymphoblastic leukemia and non-Hodgkin lymphomas." (PMID 34681778, 2021). "Incorporation of asparaginase into treatment for acute lymphoblastic leukemia (ALL) has reduced relapse rates and improved survival for children." (PMID 34528411, 2021).
acute lymphoblastic leukemia (continued). "Asparaginase depletes extracellular asparagine in the blood and is an important treatment for acute lymphoblastic leukemia (ALL) due to asparagine auxotrophy of ALL blasts." (PMID 34267184, 2021). "Combined treatment with asparaginase and corticosteroids leads to hypertriglyceridemia in up to 67% of patients receiving treatment for acute lymphoblastic leukemia." (PMID 33324553, 2020). "Asparaginase is indeed well known as key in the treatment of acute lymphoblastic leukemia and its potential as “anti-colon cancer protein” has been recently proposed." (PMID 31417524, 2019). "In this review, we highlight the most important findings reported in studies of the pharmacogenetics of asparaginase related complications and treatment outcome in acute lymphoblastic leukemia." (PMID 35582721, 2019). "First, asparagine levels are critical for many types of cancer, as shown most dramatically for acute lymphoblastic leukemia (ALL) where asparaginase (ASNase) is used to deplete plasma asparagine levels in chemotherapy." (PMID 30464009, 2018). "The major causes of AP are alcohol abuse and gallstone complications, but it also occurs as an important side effect of the standard asparaginase-based therapy for childhood acute lymphoblastic leukemia." (PMID 29893744, 2018). "Asparaginase, a bacterial hydrolytic enzyme is used as an antineoplastic agent in humans as part of the chemotherapy regimen of acute lymphoblastic leukaemia (ALL), acute myeloid leukaemia (AML) and non-Hodgkin’s lymphoma." (PMID 29584669, 2018). "Polymorphisms of asparaginase pathway genes are related with asparaginase-related complications in children with acute lymphoblastic leukemia, probably by affecting early response to treatment." (PMID 28629319, 2017). "Asparaginase is an essential element in the successful treatment of acute lymphoblastic leukaemia, the most common type of cancer affecting children, but AP is a side-effect occurring in about 5–10% of cases." (PMID 27377732, 2016). "This has led to the use of asparaginase, the enzyme that converts asparagine to aspartate and ammonia, for the treatment of childhood acute lymphoblastic leukemia (ALL)." (PMID 26130389, 2015). "Very little information has been reported about using of plant asparaginase in treatment of acute lymphoblastic leukemia." (PMID 26413120, 2015). "We report a large pancreatic pseudocyst in a 4-year old child, which developed following therapy with PEG-Asparaginase for acute lymphoblastic leukemia." (PMID 25628993, 2015). "A 13-year-old boy diagnosed with acute lymphoblastic leukemia was immediately started with treatment (prednisone, dexamethasone, vincristine, asparaginase, and daunorubicin) via a central vascular catheter ((CVC), Broviac)." (PMID 23935636, 2013). "To test the pathophysiological relevance of our findings, we turned our attention to human PDX leukemia specimens, which were derived from patients with B-precursor acute lymphoblastic leukemia treated with asparaginase-intensive combination chemotherapy on contemporary clinical trials." (PMID 40131931, 2025). "It is mostly, but not always, associated with the administration of asparaginase, an essential component of intensive therapy for acute lymphoblastic leukemia." (PMID 39123368, 2024). "Asparaginase is a large tetramericprotein assembly, currently used against acute lymphoblastic leukemia.Here, a gadolinium(III)-DOTA derivative has been conjugated to asparaginase,and its relaxation properties have been investigated to assess itsefficiency as a possible theranostic agent." (PMID 36458591, 2022). "However, many studies have demonstrated that acute lymphoblastic leukemia can still be inhibited by asparaginase even when ASNS is expressed." (PMID 36405587, 2022).